MITF (melanocyte inducing transcription factor)
Diseases named in the same sentence as MITF in open-access papers (continued):
Sharing a sentence is not in itself a finding about the gene and the disease.
melanoma (continued). "Thus, it will be of interest to test whether DNA damage per se or susceptibility to DNA damage caused by inhibition of DEK or MITF in melanoma cells are mediated by the depletion of dNTP pools, and whether upregulation of TS and RR suppresses these phenotypes." (PMID 23249808, 2012). "Moreover, MITF expression is associated with the 246 melanoma-specific gene expressions." (PMID 20925909, 2010). "Finally, downregulation of MiTF and subsequent induction of apoptosis and inhibition of cell growth may underlie the limited expansion of melanoma cells when grown in a skeletal muscle microenvironment." (PMID 20174581, 2010). "Thus, multiple factors in addition to MITF may be responsible for the differential expression of developmental genes associated with the invasive potential of metastatic melanoma cells." (PMID 20041153, 2009). "Emerging evidence suggests that sphingolipids play a role in melanoma dedifferentiation by regulating MITF." (PMID 41596686, 2026). "Microphthalmia-associated transcription factor (MITF) is crucial for development and survival of melanocytes and serves as a lineage-specific oncogene that is amplified in 10-20% of melanomas." (PMID 42268265, 2026). "Wnt/β-catenin signaling pathway exerts a regulatory influence on both ferroptosis and the efficacy of immunotherapy in melanoma, by modulating MITF and its downstream targets, PGC1α and SCD1." (PMID 41596686, 2026). "In mouse melanoma cells, DHC treatment significantly downregulated the melanogenesis-related genes: Microphthalmia-associated Transcription Factor (MITF), tyrosinase (TYR), and Tyrosinase-related protein 1 (TRP1) compared with the α-MSH control (p < 0.05)." (PMID 41596671, 2026). "MITF is the production of antiapoptotic Bcl‐2 gene, and it also related to the survival of melanocytes and melanoma cells." (PMID 41492362, 2026). "A-SMase promotes MAPK activation and MITF degradation, while AC, a direct MITF transcriptional target, is crucial for the phenotypic switch from invasive to proliferative melanoma cells." (PMID 41596686, 2026). "CRTC1::TRIM11 cutaneous tumors are an emerging subset of MITF pathway-activated neoplasms that typically present as dermal nodules and can closely mimic clear cell sarcoma or malignant melanoma." (PMID 42015602, 2026). "This activation promotes a differentiated/proliferative MITF-high phenotype in melanoma cells, which exhibit enhanced spreading in a rigid collagen matrix." (PMID 40399946, 2025). "For example, defects in the Wnt/β-catenin signaling pathway exacerbate ferroptosis in melanoma by regulating MITF." (PMID 39689154, 2025). "Further insights into RNA helicases reveal the role of DDX3X in enhancing the translation of MITF, a transcription factor that suppresses melanoma invasiveness when highly expressed." (PMID 39823244, 2025). "This enhanced staining was most prominent in the combination group (PTX 60 mg/kg + NCTD 3 mg/kg), corroborating the quantitative data and suggesting that both monotherapy and combination therapy promote MITF upregulation in melanoma tissues." (PMID 40806647, 2025). "SIRT5 is responsible for the proliferation and survival of BRAF-mutant melanoma cells through repressing apoptosis as a consequence of chromatin modification and expression of survival factors such as MITF and c-Myc." (PMID 39935431, 2025). "Unlike undifferentiated cells, differentiated keratinocytes induce melanoma invasion through a Notch-dependent pathway, involving inhibition of MITF, a gene found to be dysregulated across all analyzed melanoma subtypes." (PMID 41465101, 2025). "In melanoma, miRNAs collectively target genes like MITF, a transcriptional target of SOX10, to fine‐tune its expression and regulate cell proliferation and migration pathways." (PMID 40458894, 2025).
melanoma (continued). "The microphthalmia-associated transcription factor (MITF) regulates antigen presentation and the expression of co-inhibitory receptors in melanoma cells, creating an immune environment that limits the infiltration of immune cells like TILs." (PMID 40872475, 2025). "In melanoma cells, MITF typically translocates to the nucleus, where it binds to DNA and regulates the expression of genes involved in melanocyte differentiation, proliferation, and survival." (PMID 41465475, 2025). "SOX10 is particularly important in melanoma due to its regulatory influence on the MITF pathway, with evidence of direct cross-activation between SOX10 and MITF." (PMID 41155720, 2025). "Mechanistically, we uncover a novel chromatin-localized interaction between BRD4 and MITF in melanoma." (PMID 40809945, 2025). "MITF expression is critical for determining melanoma phenotypes and contributes to tumor cell plasticity." (PMID 40458894, 2025). "This coordination links mTORC1 signaling with the endosomal–lysosomal system, making MITF a key regulator of melanoma plasticity and progression via control of TFE3, TFEB, and endosomal–lysosomal pathways." (PMID 41155412, 2025). "The regulatory landscape is further enriched by miRNAs that function as tumor suppressors by modulating SOX10, MITF, and their downstream effectors in melanoma." (PMID 40458894, 2025). "The results demonstrated that fisetin treatment led to a marked reduction in MITF and tyrosinase protein levels in both melanoma and α-MSH-stimulated human melanoma cells." (PMID 41373883, 2025). "By refining the BRISK classification to more accurately capture variations in TIL distribution, our study aims to elucidate the complex interplay between MITF expression and the immune microenvironment in melanoma." (PMID 39976551, 2025). "Here, we identified lncRNAs expressed from equivalent regions in the human and zebrafish genomes in which the human orthologue is expressed in melanoma and targeted by the key MITF transcription factor." (PMID 41336739, 2025). "In conclusion, fisetin significantly inhibits melanin production in human melanoma cells by modulating key melanogenic regulators, including MITF and β-catenin." (PMID 41373883, 2025). "Microphthalmia transcription factor (MITF) is a key regulator of the melanogenesis machinery and plays a critical role in the switch between proliferative (MITF-high) and invasive (MITF-low) melanoma phenotypes." (PMID 41155412, 2025). "It is now known that the MITF/PGC1α axis in melanoma represents a key node in the metabolic switch of the tumor cell, allowing a fast adaptive response to external stimuli." (PMID 40573249, 2025). "SOX10, MITF, and other key factors in melanoma development are part of these motifs, impacting tumor progression and therapy resistance." (PMID 40458894, 2025). "Fluorescence microscopy observations indicated that BuOH fraction treatment significantly inhibited the translocation of MITF into the nucleus compared to B16F10 melanoma cells treated exclusively with α-MSH." (PMID 41309371, 2025). "MITF has been most extensively studied in melanoma, where it functions as a master regulator of melanocyte biology." (PMID 41168571, 2025). "In contrast, amelanotic melanoma cells tend to be less differentiated and are often characterized by reduced expression of pigmentation-related genes (e.g., MITF, TYR) and alternative oncogenic alterations." (PMID 40649764, 2025). "We also reviewed the current state of knowledge on the molecular interplay between SOX10, MITF, miRNAs, and other interactors in melanoma." (PMID 40458894, 2025). "The results demonstrated that fisetin treatment significantly promoted proteasomal degradation of MITF in both melanoma and α-MSH-induced melanoma cells by 2.5-fold and 5-fold, respectively." (PMID 41373883, 2025).
melanoma (continued). "Resistance to BRAF inhibition (BRAFi) is a significant clinical obstacle, as certain melanoma cells can downregulate key regulators of melanocyte differentiation, such as MITF, and upregulate RTKs like AXL and EGFR." (PMID 40386826, 2025). "This study reinforces the significance of MITF expression in the melanoma immune microenvironment and its potential as a biomarker for therapeutic response." (PMID 39976551, 2025). "Within the melanoma microenvironment, aberrant ERK signaling—driven by oncogenic BRAF mutations—induces MITF degradation via a ubiquitin-mediated proteasomal pathway, contributing to dysregulated melanocytic lineage commitment and tumor progression." (PMID 40427124, 2025). "In melanoma, HIF-1α can stimulate the expression of the melanocyte-specific transcription factor MITF (microphthalmia-associated transcription factor) even in hypoxia, which paradoxically favors tumor growth." (PMID 40806546, 2025). "The analysis revealed that melanomas classified under the BRISK B category exhibited the highest MITF expression, often exceeding 50%." (PMID 39976551, 2025). "DIRC3 is a MITF-repressed lncRNA that blocks the anchorage-independent growth of melanoma cells whilst the MITF activated lncRNA LENOX promotes melanoma cell survival and resistance to MAP kinase inhibitors." (PMID 41336739, 2025). "In our network, we searched for three‐node network motifs containing SOX10 and miRNAs and identified a coherent FFL involving SOX10, MITF, and miR‐155 in melanoma." (PMID 40458894, 2025). "This methodology facilitates a deeper understanding of the regulation of SOX10 and MITF by miRNAs in melanoma." (PMID 40458894, 2025). "MITF regulates melanocyte development, melanoma progression, and immune responses, with its activity levels determining cell phenotypes." (PMID 40458894, 2025). "Collectively, these results complement the existing models based on the dynamic interplay of known melanoma lineage-defining transcription factors like MITF, SOX10, BRN2, and AXL, by adding KPC1 as a crucial checkpoint." (PMID 41429767, 2025). "MITF is required for melanocytic oncogenesis and was found to be one of the SE occupants in melanoma." (PMID 41392986, 2025). "Treatment of B16F10 melanoma cells with oxyresveratrol suppressed melanogenesis through the down-regulation of the MC1R/cAMP/MITF signaling pathway." (PMID 40594379, 2025). "Phosphorylation of microphthalmia-associated transcription factor (MITF) at amino acid 73 by ERK has been reported to cause its degradation, which is a transcription factor unique for melanoma development and resistance." (PMID 40063190, 2025). "The mechanisms that drive adaptive resistance in melanoma are primarily composed by resetting the activity of the ERK1/2 pathway, upregulation of receptor tyrosine kinases and upregulation of MIcrophthalmia-associated Transcription Factor (MITF)." (PMID 40872623, 2025). "Further, AR signaling was reported to drive melanoma invasiveness through tumorigenic fucosylation or the MITF/AXL axis." (PMID 41228208, 2025). "MITF functions in a biphasic manner, where both high and low expression states can contribute to melanoma progression through different mechanisms." (PMID 41465475, 2025). "MITF levels are inversely correlated with transcription factor 4 (TCF4) and EZH2, which promote the mesenchymal-like state of melanoma associated with the suppression of antigen presentation." (PMID 40108693, 2025). "Meanwhile, in MITF-low invasive melanoma, transcription factor EB (TFEB) and TFE3 drive lysosomal biogenesis and function to support tumor growth and invasiveness through nutrient recycling and metabolic adaptation." (PMID 41155412, 2025). "In melanoma, its expression is activated by Wnt/β-catenin and MITF, and as expected, ICG-001 treatment suppressed ABCB5 mRNA as well as expression of ABCB5 immunoreactive isoforms in both our VemR models." (PMID 40558548, 2025).
melanoma (continued). "In the current study, two types of alfalfa seed extract exerted significant melanin inhibition in mouse melanoma cells in association with decreased protein and mRNA levels of the melanogenesis‐related factors, tyrosinase, TRP1 and MITF." (PMID 40524653, 2025). "In our network, the most pertinent hubs are SOX10 and MITF, as both TFs play a crucial role in melanoma." (PMID 40458894, 2025). "Whilst MITF acts as a rheostat to govern the generation of different melanoma cell states in response to changes in the microenvironment, broad DANCR expression suggests additional modes of regulation." (PMID 41336739, 2025). "Apart from melanoma, studies have connected MITF with other oncogenic processes, such as pancreatic cancer, hepatocellular carcinoma, and breast cancer." (PMID 40343114, 2025). "The link between both genes was supported by analyzing published datasets, which revealed reduced DDIT4L expression in melanocytes and melanoma cells after siRNA-mediated knockdown of MITF." (PMID 40918647, 2025). "MITF levels were also significantly higher in advanced clinical stages, with melanomas in stages 0–IIa showing a median expression of 14% (95% CI: 2%–52%) compared to 47% (95% CI: 14%–87%) in stages III–IV (H ═ 8.41, P ═ 0.03)." (PMID 39976551, 2025). "DCS significantly downregulated the expression of key melanogenic enzymes including tyrosinase, TRP-1, and TRP-2, as well as the master transcription factor MITF, in melanoma cells." (PMID 40869042, 2025). "Analysis of key melanoma signature markers revealed that MITF and MLANA were highly expressed in Cluster 1, indicating a differentiated state." (PMID 40386826, 2025). "This chromatin complex plays a pivotal role in selective recruitment of BRD4 and MITF to different genomic loci in melanoma cells." (PMID 40809945, 2025). "The TFE3-related transcription factor MITF was shown to drive OxPhos in melanoma through regulation of PPARGC1A, but also the non-coding RNAs SAMMSON and LENOX." (PMID 40148585, 2025). "In melanoma, MITF directly regulates SCD1 expression and MITFhigt cells are more susceptible to SCD1 treatment by blocking their proliferation." (PMID 40573249, 2025). "Honokiol inhibits the oncogenic KRT18 protein in melanoma and prevents recurrence of advanced melanoma using the β-catenin/MITF axis via prompt calpain-10 and CCAAT homologous protein (CHOP/GADD153) regulated cascades." (PMID 40943669, 2025). "Meanwhile, miR‐211, originating from the TRPM1 gene, is involved in melanoma cell adaptation to hypoxia by regulating the MITF pathway." (PMID 39823244, 2025). "A Western blot analysis was conducted to investigate the effects of 2,6′-DMC on MITF protein expression in B16F10 melanoma cells." (PMID 39996806, 2025). "In BRAF-mutant melanomas, loss of the CDKN2A gene is typical, but amplification of MITF and CD274 (coding for PD-L1; programmed death ligand 1) is relatively common." (PMID 40361349, 2025). "As different melanoma subtypes can exhibit distinct MITF-dependent phenotypes, the biological significance of the observed MITF increase requires careful interpretation." (PMID 41465475, 2025). "MITF is a key oncogene in human melanoma, where it plays a critical role in melanogenesis, melanocyte survival, and tumor progression." (PMID 40647405, 2025). "SOX10 is well known to promote a more invasive and dedifferentiated melanoma phenotype, in part by sustaining low-MITF, high-motility cell states." (PMID 41465475, 2025). "MITF is also a major player in melanoma progression, influencing both the melanoma cell differentiation state and plasticity, contributing to high tumor heterogeneity." (PMID 40973828, 2025).
melanoma (continued). "SIRT1 overexpression was initially associated with vemurafenib resistance in BRAFV600E melanoma, and SIRT1 mediated MITF-induced melanoma proliferation." (PMID 39935431, 2025). "Under hypoxic microenvironmental pressures, melanoma cells can undergo phenotype switching between MITF-high and MITF-low states, contributing to a population of slow-cycling, therapy-resistant cells." (PMID 40977706, 2025). "UCHL1 overexpression in melanoma cells activates UPS-mediated degradation, consequently inhibiting microphthalmia-associated transcription factor (MITF) expression and reducing melanin production." (PMID 40860809, 2025). "Nevertheless, YAP/TAZ suppresses MITF expression and induces a de-differentiated melanoma phenotype in a fibroblast-rich matrix." (PMID 40399946, 2025). "Other findings showed that the inhibitory action of fisetin on the β-catenin/MITF signaling pathway suggests its potential as an effective agent against 451Lu human melanoma cells." (PMID 41373883, 2025). "Here, we show that the expression of ERRFI1 was upregulated in melanoma and negatively correlated with the expression of melanocytic differentiation markers, such as MITF and TYR." (PMID 41044875, 2025). "We reveal that human DANCR is regulated by the cancer causing MITF and c-MYC transcription factors in melanoma, promotes human melanoma cell proliferation and migration and is associated with poor patient survival." (PMID 41336739, 2025). "This interpretation was confirmed using human 501mel melanoma cells expressing Dox-inducible murine MITF, where induction of MITF suppressed all differentiation-associated genes." (PMID 41275493, 2025). "The role of DIRC3 in tumour suppression in melanoma is based on the modulation of transcriptional networks governed by MITF and SOX10." (PMID 41463281, 2025). "We next examined a set of genes relevant to melanocyte/melanoma biology known to be directly bound and positively regulated by MITF, including Ppargc1a16,17 and Scd1." (PMID 41275493, 2025). "Our analysis of the Tirosh scRNA-seq data revealed divergent melanoma transcriptional phenotypes that correlate with low MITF expression." (PMID 38183207, 2025). "Phenotype switching in melanoma and neuroblastoma illustrates this principle: cells toggle between MITF^high proliferative and MITF^low invasive states, mirroring CSC dormancy versus migratory phenotypes." (PMID 41462674, 2025). "MITF can also induce the expression of survival genes and help melanoma cells switching to alternative growth pathways, further enhancing resistance to therapy." (PMID 40872623, 2025). "The regulatory loop formed by MITF and Rec maintains the proliferation of melanoma cells by inhibiting epithelial–mesenchymal transition (EMT) but inhibits their transition to an aggressive phenotype." (PMID 40722734, 2025). "Microphthalmia-associated transcription factor (MITF) is a lineage-specific transcription factor for melanocytes and melanoma." (PMID 40722734, 2025). "The increase in the incidence of skin melanoma suggests the necessity of devising new therapeutic strategies, e.g., involving the WNT/β-catenin signalling pathway and the MITF transcription factor responsible for melanoma cell invasion." (PMID 40943669, 2025). "In melanomas, MITF is expressed in 56% to 100% of cases when excluding desmoplastic and spindle cells melanomas." (PMID 40507250, 2025). "On the other hand, TINCR acts upstream of MITF to repress its expression and block the spread of melanoma whilst SAMMSON is frequently co-amplified with MITF in melanoma and is essential for melanoma cell proliferation and survival." (PMID 41336739, 2025). "In an ADRN PDX model (MYCN amplified) that developed indisulam resistance, cancer cells lost their ADRN features and were enriched with expression features of melanoma markers such as MITF." (PMID 40962798, 2025).